MIR6812 (microRNA 6812)
Synonyms: hsa-mir-6812
Gene: MicroRNA gene on chromosome 20 (45,425,510 to 45,425,573, forward strand). Ensembl gene ENSG00000273555.
Homologues: Orthologues: chimpanzee MIR6812 (100% identical), macaque MIR6812 (100% identical).
Diseases named in the same sentence as MIR6812 in open-access papers:
MIR6812 is named in the same sentence as 2 diseases in open-access papers, as found by Europe PMC text mining. Sharing a sentence is not in itself a finding about the gene and the disease. The quoted sentences say what the papers report.
lupus nephritis (1 paper, 2022). Glomerulonephritis in the context of systemic lupus erythematosus. "Taken together, our data suggested that circMTND5 might contribute to mitochondrial injury and further promote renal fibrosis by sponging MIR6812; further, MIR6812 regulate UCP2 and PGC-1α to participate renal fibrosis in lupus nephritis." (PMID 36267809, 2022).
renal fibrosis (1 paper, 2022). A final common manifestation of a wide variety of chronic kidney diseases characterized by glomerulosclerosis and tubulointerstitial fibrosis. "The interference of the circMTND5/MIR6812 axis may offer potential novel avenues for RNA therapeutics to treat renal mitochondrial injury and renal fibrosis in LN." (PMID 36267809, 2022).